PLXNB3 (plexin B3)
Description:
Receptor for SEMA5A that plays a role in axon guidance, invasive growth and cell migration. Stimulates neurite outgrowth and mediates Ca(2+)/Mg(2+)-dependent cell aggregation. In glioma cells, SEMA5A stimulation of PLXNB3 results in the disassembly of F-actin stress fibers, disruption of focal adhesions and cellular collapse as well as inhibition of cell migration and invasion through ARHGDIA-mediated inactivation of RAC1.
Synonyms: PLXN6; PLEXR; PLEXB3
Tractability: Antibody: UniProt places it where antibodies can reach, with high confidence; its Gene Ontology location is reachable by antibodies, with high confidence; UniProt predicts a signal peptide or a membrane-spanning region. PROTAC: ubiquitination databases record sites on it.
Gene: Protein-coding gene on chromosome X (153,764,186 to 153,779,346, forward strand). Ensembl gene ENSG00000198753.
Subcellular location: Cell membrane
Pathways (Reactome):
Developmental Biology: Other semaphorin interactions
Gene Ontology:
Molecular function: cell-cell adhesion mediator activity; protein binding; protein domain specific binding; semaphorin receptor activity; Rho GDP-dissociation inhibitor binding
Biological process: cell chemotaxis; homophilic cell-cell adhesion; negative regulation of cell adhesion; negative regulation of cell migration; negative regulation of GTPase activity; positive chemotaxis; positive regulation of endothelial cell proliferation; positive regulation of neuron projection development; semaphorin-plexin signaling pathway; negative regulation of lamellipodium assembly; positive regulation of axonogenesis; regulation of cell shape; synapse assembly
Cellular component: cell surface; plasma membrane; semaphorin receptor complex
Homologues: Orthologues: chimpanzee PLXNB3 (99% identical), pig PLXNB3 (86% identical), dog PLXNB3 (86% identical), guinea pig PLXNB3 (86% identical), rat Plxnb3 (85% identical), mouse Plxnb3 (84% identical), rabbit PLXNB3 (80% identical), tropical clawed frog plxnb3 (53% identical), zebrafish plxnb3 (51% identical), Drosophila melanogaster PlexB (32% identical), Drosophila melanogaster PlexA (32% identical), Caenorhabditis elegans plx-1 (29% identical), and 1 more. Paralogues in human: PLXNB1 (51% identical), PLXNB2 (39% identical), PLXNA1 (34% identical), PLXND1 (34% identical), PLXNA2 (33% identical), PLXNA4 (32% identical), PLXNA3 (32% identical), PLXNC1 (21% identical).
Diseases named in the same sentence as PLXNB3 in open-access papers:
PLXNB3 is named in the same sentence as 31 diseases in open-access papers, as found by Europe PMC text mining. Sharing a sentence is not in itself a finding about the gene and the disease. The quoted sentences say what the papers report.
glioma (11 papers, 2011 to 2023). A benign or malignant brain and spinal cord tumor that arises from glial cells (astrocytes, oligodendrocytes, ependymal cells). "Mutations in XIE genes USP9X, NLGN4x, PLXNB3 (involved in axonal guidance and glioma invasion), SYAP1, SRPX2, and ZFX (ZFX-SMARCA1 fusion) occurred in non-MN1-BEND2, predominantly female cases." (PMID 35440587, 2022). "This group also demonstrated that the SEMA5A/Plexin-B3 axis causes the astrocytic differentiation of glioma cells." (PMID 33669221, 2021). "This latter cohort included several genes relevant to progenitor development and migration, including Arx, Dbx2, the semaphorin receptor plexin B3, and the cytoskeletal adaptor Stmn3, which has recently been linked to glioma motility." (PMID 27213272, 2016). "For example, Plexin-B3, acting through a variety of small GTPases belonging to Ras and Rho families, is involved in the regulation of cell motility and metastasis in glioma." (PMID 38133141, 2023). "Li and Lee found that Sema5A inhibited the Rac1 GTPase through stimulation of plexin-B3, which resulted in the inhibition of glioma cell migration and invasion." (PMID 25780417, 2015). "A recent report that investigates the significance of Sema5A and plexin-B3 in glioma has also shown their suppression of Rac1 activation, though through a different mechanism." (PMID 23050142, 2012). "Recently, Sema5A has been shown to suppress human glioma cell migration and invasion in a plexin-B3- and Rac1-dependent manner." (PMID 23050142, 2012). "Studies of Plexin-B3 have demonstrated that Plexin-B3 regulates Rac activation in a ligand-dependent manner in glioma cells by binding to RhoGDI, which prevents Rac activation and reduces cell motility." (PMID 21966369, 2011). "Similar to our observation, Plexin-B3 and ligand SEMA5A were found to inhibit human glioma cell invasion." (PMID 33669221, 2021). "In contrast, our analyses did not reveal correlations of Plexin-B1 expression levels and glioma grade/type or patient survival, and only weak correlations for Plexin-B3 with lower Plexin-B3 levels corresponding to worse survival." (PMID 25762646, 2015).
breast carcinoma (4 papers, 2020 to 2023). "Thus, we hypothesized that the tumor Plexin B3-neuron Sema5A interaction mediates sensory nerve-driven breast cancer cell migration." (PMID 36333352, 2022). "Recent studies have identified HIF-1-dependent expression of PLXNB3, NARF, and TERT in hypoxic breast cancer cells." (PMID 37768037, 2023). "This is corresponding to their prediction of patient survival outcomes with PLXNB1 showing favorable prognosis, while PLXNB3 and PLXND1 show poor prognosis for both OS and PFI in breast cancer tumors." (PMID 32640719, 2020). "In contrast, the role of PLXNB3 in CRC has not been yet investigated, although it was found to be overexpressed in breast cancer." (PMID 35721480, 2022). "Surprisingly, genes PLXNB1, B3, and D1 showed no significant differential expression in breast cancer tumors compared to normal, but PLXNB1 showed favorable prognosis, and PLXNB3 and PLXND1 showed poor prognosis for both OS and PFI." (PMID 32640719, 2020).
gastric carcinoma (3 papers, 2015 to 2021). A carcinoma that arises from epithelial cells of the stomach. "However, overexpression of Sema5A in pancreatic cancer has been shown to correlate with invasion, metastasis and increased endothelial cell proliferation, while overexpression of Sema5A and plexin-B3 are associated with the invasion and metastasis of gastric carcinoma." (PMID 25780417, 2015). "In addition, the overexpression of Sema5A and plexin-B3 in gastric carcinoma have been shown to correlate with the invasion and metastasis of tumors." (PMID 25780417, 2015). "Our observations are supported by a study of samples from gastric carcinoma patients illustrating elated expression levels of both SEMA5A and its receptor Plexin-B3 in primary gastric carcinoma and lymph node metastasis in comparison to the non-neoplastic tissue." (PMID 29464045, 2018).
congenital heart disease (2 papers, 2024 to 2025). A heart disease that is present at birth. "Recently, an association of congenital heart disease and neurodevelopmental problems was linked to PLXNB3 missense mutations." (PMID 40662097, 2025). "Recently, PLXNB3 mutations were identified in congenital heart disease associated with neurodevelopmental disabilities, further suggesting that Plexin B3 be important for early neurodevelopment." (PMID 38628398, 2024).
hepatocellular carcinoma (2 papers, 2015 to 2021). A malignant tumor that arises from hepatocytes. "However, the expression and role of plexin-B3 in hepatocellular carcinoma (HCC) is yet to be investigated." (PMID 25780417, 2015).
pancreatic cancer (2 papers, 2015 to 2021). "We saw the tumor-specific and metastasis-specific roles of Semaphorin-5A, a ligand of Plexin-B3, in pancreatic cancer." (PMID 33669221, 2021). "Our group has identified Semaphorin-5A (SEMA5A)/Plexin-B3 as an attractive targetable complex for pancreatic cancer (PC) metastasis." (PMID 33669221, 2021). "Previously our group identified Semaphorin-5A (SEMA5A), the ligand of Plexin-B3, involved in organ-specific homing of pancreatic cancer (PC) cells and plays a significant role in PC angiogenesis and metastasis." (PMID 33669221, 2021). "Our present study had an investigative approach towards exploring the possible role of Plexin-B3 in pancreatic cancer." (PMID 33669221, 2021). "We utilized a human tissue microarray consisting of a pancreatic tumor and normal pancreas cores to analyze the pathological expression of Plexin-B3 in PC." (PMID 33669221, 2021). "A qualitative immunochemistry analysis of Plexin-B3 expression in the KC pancreatic tumor progression model shows an initial increase of Plexin-B3 staining until 20 weeks, followed by a decrease in Plexin-B3 expression in later stages." (PMID 33669221, 2021). "To analyze the expression of Plexin-B3 at different metastatic sites in PC patients, we utilized the tissue microarray containing matched primary pancreatic tumor cores with the corresponding liver metastatic site cores." (PMID 33669221, 2021). "Additionally, the correlation of Plexin-B3 expression between the matched primary pancreatic tumor cores and liver metastatic site cores was 0.56." (PMID 33669221, 2021). "To gain an insight into the Plexin-B3 expression in the pancreatic ductal adenocarcinoma (PDAC) disease progression model, we analyzed pancreatic tumor tissues derived from the KrasG12D;Pdx1-Cre (KC) mouse model at different ages (10, 20, 30, and 50 weeks)." (PMID 33669221, 2021). "However, the IHC analysis of Plexin-B3 expression in the mouse pancreatic tumor progression model showed an initial increase of Plexin-B3 staining until 20 weeks, followed by a decrease in Plexin-B3 expression in the later stages with a positive Plexin-B3 expression in normal mice pancreas." (PMID 33669221, 2021). "Nevertheless, the range of Plexin-B3 showed a higher expression trend in metastatic liver sites in comparison with primary pancreatic tumors; however, this was not a statistically significant observation." (PMID 33669221, 2021).
CADDS (1 paper, 2017). CADDS is a rare, genetic, neurometabolic disease characterized by severe intrauterine growth retardation, failure to thrive, profound neonatal hypotonia, severe global development delay, elevated very long chain fatty acids in plasma, and neonatal cholestasis leading to hepatic failure and death.
cervical cancer (1 paper, 2018). A primary or metastatic malignant neoplasm involving the cervix. "Semaphorin 5A also increased cervical cancer cell invasion by stimulating the expression and activity of matrix metalloproteinase-2 and matrix metalloproteinase-9 via PI3K/AKT and plexin-B3." (PMID 29977159, 2018).
dementia (1 paper, 2024). Loss of intellectual abilities interfering with an individual's social and occupational functions. "Our findings included well-known dementia-associated protein biomarkers, such as BMP4, CD200, MANF, PLXNB1, PLXNB3, and SMPD1 for AD and BCAN, NCAN, and THY1 for VD, as well as uncovering novel proteins associated with AD or VD." (PMID 39226887, 2024).
epilepsy (1 paper, 2022). A brain disorder characterized by episodes of abnormally increased neuronal discharge resulting in transient episodes of sensory or motor neurological dysfunction, or psychic dysfunction. "Among them, IPA revealed that 5 genes (Gfap, Gmppa, Tubb2b, SLC22a8 and Plxnb3) were related to epilepsy or neurodevelopmental disorders." (PMID 35474103, 2022). "Interestingly, 5 genes (Gfap, Gmppa, Tubb2b, SLC22a8 and Plxnb3) among the DEGs are known to be related to epilepsy or neurodevelopmental disorders." (PMID 35474103, 2022).
lung adenocarcinoma (1 paper, 2022). A carcinoma that arises from the lung and is characterized by the presence of malignant glandular epithelial cells. "Finally, SFTPA1, PLXNB3, BIRC5, CBLC, and ACVRL1 were screened out based on the intersection between the top 10 differentially expressed genes in lung adenocarcinoma (LUAD) and lung squamous cell carcinoma (LUSC)." (PMID 34181042, 2022).
melanoma (1 paper, 2020). A malignant, usually aggressive tumor composed of atypical, neoplastic melanocytes. "In addition, NRP2, PLXNA1, PLXNC1, and PLXNB3 were found to be all positively associated with cell sensitivity to Vemurafenib, which is used for the treatment for late-stage melanoma." (PMID 32640719, 2020). "Furthermore, NRP2, PLXNC1 and PLXNB3 were also positively associated with cell sensitivity to Dabrafenib, which is the treatment for late-stage melanoma and metastatic non-small cell lung cancer with BRAF V600E or V600K mutations." (PMID 32640719, 2020).
prostate adenocarcinoma (1 paper, 2022). "In the majority of cancers, such as CCA and prostate adenocarcinoma, PLXNB3 was more associated with poor survival." (PMID 35847907, 2022).
prostate carcinoma (1 paper, 2021). A carcinoma that arises from epithelial cells of the prostate gland. "Previously, our group showed a higher expression of plexin-B3 in the metastasis of prostate cancer in comparison to the primary tumor." (PMID 33669221, 2021).
Sepsis (1 paper, 2023). Sepsis is defined as life-threatening organ dysfunction caused by a dysregulated host response to infection. "Expression of sepsis-specific biomarkers PLXNB3, ITGB3, CETP, CMTM5 and PF4 correlated positively with each other at the Day1 time point and to a slightly lesser degree with MIA and CRP." (PMID 38332914, 2023).
triple-negative breast carcinoma (1 paper, 2023). An invasive breast carcinoma which is negative for expression of estrogen receptor (ER), progesterone receptor (PR), and human epidermal growth factor receptor 2 (HER2). "Another example is the finding that in mice triple negative breast cancer tumors have more sensory neurons and the axon guidance molecule Plexin B3 mediates cancer cells’ adhesion and migration on sensory nerves." (PMID 36650218, 2023).
tumor (12 papers, 2015 to 2023). "Our results suggest that the loss of Plexin-B3 enhanced the escape of a tumor cell from the primary tumor by increasing the cancer cell’s motility and invasiveness, thereby resulting in a low tumor burden with high metastasis." (PMID 33669221, 2021). "In contrast, in triple-negative breast cancer cells, plexin-B3 knockdown inhibited cancer cell growth and cell migration and invasion, as well as tumor progression in animal models." (PMID 37627074, 2023). "In our study, we have demonstrated that M2 TAM-derived secreted protein SEMA5A would interact with tumor cell membrane located in PLXNB3 and thus induce tumor cell proliferation for metastatic niche expansion via enhancing the Warburg effects." (PMID 36741230, 2023). "The outgrowth facilitation PLXNB3 exerted on tumor cells was triggered by SEMA5A which was also consolidated by SEMA5A-ΔTSP." (PMID 36741230, 2023). "The results of ex vivo on tissues harvested from KPC mice have also confirmed these results.We have demonstrated that treatment of rSEMA5A- on PLXNB3-expressed tumor cell lines upregulated glucose consumption and lactate production." (PMID 36741230, 2023). "We next performed IF staining on these tissues and demonstrated that it was PLXNB3 which located on CK19+ metastasized tumor cells in niches." (PMID 36741230, 2023). "It has been noticed that PLXNB3 were upregulated in most cell lines, indicating the tumor resident behavior of which, while SEMA5A was maintained at a relative low level for its source was usually exogenous." (PMID 36741230, 2023). "While we focused on Plexin B3, it will be important to perform further experiments to better understand if and how these other pathways are also involved in mediating tumor cell–nerve interactions." (PMID 36333352, 2022). "Apart from visualizing Plexin-B3 expression in the tumor and surrounding stroma, we also explored Plexin-B3 expression in sequenced PC tumors through the online Michigan Portal for the Analysis of NGS Data (MiPanda)." (PMID 33669221, 2021). "We found Plexin-B3 expression localized on the membrane of tumor cells with positive staining in the surrounding tumor stroma." (PMID 33669221, 2021). "Our in vitro functional assays, such as the cell cycle analysis and low BCL2 expression in Plexin-B3 knockdown cells, explain our in vivo observation of a lower tumor burden with less Ki-67-positive cells in mice injected with Plexin-B3 knockdown cells." (PMID 33669221, 2021). "In conclusion, we report novel insights into the pathological expression and functional role of Plexin-B3 in PC tumor growth and metastasis." (PMID 33669221, 2021). "We observed a higher Plexin-B3 expression in PC tumor cores than the normal pancreas, and different metastatic sites were positive for Plexin-B3 expression." (PMID 33669221, 2021). "In the tumor cores, both cancer cells and tumor stroma were positive for Plexin-B3 expression, and different tumors demonstrated a range of Plexin-B3 intensity." (PMID 33669221, 2021). "A growing body of evidence suggests that SEMA5A plays an important role in tumor progression through its interaction with plexin-B3." (PMID 29977159, 2018). "Plexin-B3 positive staining was observed in the membrane and cytoplasm of the tumor cells and hepatocytes." (PMID 25780417, 2015). "Additionally, plexin-B3 knockdown was found to promote the migration and invasion of pancreatic cancer cells and to induce tumor metastasis in mouse models." (PMID 37627074, 2023). "Further staining also elucidated that PLXNB3 could facilitate cell proliferation and prevent tumor cells from apoptosis." (PMID 36741230, 2023). "Collectively, these data have demonstrated that PLXNB3 facilitated tumor burden growth in vivo." (PMID 36741230, 2023). "We have discovered that M2 type TAM-derived SEMA5A could bind to its tumor cell-expressed receptor PLXNB3 to promote tumor cell proliferation and outgrowth." (PMID 36741230, 2023).